METTL3 (methyltransferase 3, N6-adenosine-methyltransferase complex catalytic subunit)
Diseases named in the same sentence as METTL3 in open-access papers (continued):
Sharing a sentence is not in itself a finding about the gene and the disease.
cancer (continued). "Some scholars have found that METTL3 produces cancer-promoting effects through the METTL3/ZMYM1/E-cadherin axis in GC." (PMID 34246319, 2021). "Additional studies provided evidence that miR-30-5p and miR-33a target MTA1 and METTL3, respectively, hence contributing to attenuated anchorage-independent growth of cancer cells." (PMID 33435156, 2021). "As in several other forms of cancer, m6A is thought to regulate the growth and self-renewal of cells via the methyltransferase catalytic activity of METTL3." (PMID 34093133, 2021). "Accumulating evidence in recent years reveals that METTL3 plays key roles in a variety of cancer types." (PMID 34531875, 2021). "In recent years, scientists have found that METTL3 plays different roles in suppressing or promoting EMT in different cancer cells, which indicates that the regulatory effect of METTL3 is cell‐type specific." (PMID 33759344, 2021). "Recent studies have suggested that the m6A modification of many proteins plays a critical role in the development of various cancers; however, the role of METTL3 in LUAD remained unclear." (PMID 33676554, 2021). "Numerous studies have shown that METTL3 takes part in a series of pathological states, including inflammation, cancer, and immune regulation." (PMID 34295905, 2021). "It was not until recent years that increasing fact about the oncogene effect of METTL3 and its dysregulation in cancer drug resistance was displayed." (PMID 34745970, 2021). "METTL3 predominantly catalyses m6A methyltransferase system and regulates numerous processes in multiple human cancers." (PMID 33568150, 2021). "In cancer, METTL3-mediated methylation leads to epithelial mesenchymal transformation (EMT) and lung or liver metastasis in cancer patients." (PMID 34211849, 2021). "The main mechanism of dysregulation of miR-1246 in cancer is methylation of pri-miR-1246 by methyltransferase METTL3 and modulation of maturation of pri-miR-1246." (PMID 35047553, 2021). "In contrast, and as discussed further in the next section, in cancer, METTL3-mediated m6A is thought to impair differentiation and promote carcinogenesis in a variety of cancer contexts, such as acute myeloid leukemia and cutaneous squamous cell carcinoma." (PMID 34209046, 2021). "Here, we systemically summarize the interaction between METTL3 and RNAs, and illustrate the multiple functions of METTL3 in human cancer." (PMID 33879256, 2021). "For example, dysregulation of some of the more well-studied RNA modifications including m6A is known to promote oncogenesis and the m6A MTase METTL3 has been identified as a possible new cancer therapeutic target." (PMID 33313824, 2021). "These potential METTL3 targets were significantly enriched in cancer-related terms including phosphate metabolism, mitochondrion organization, apoptosis and cellular response to stress." (PMID 34631715, 2021). "Generally, METTL3, as an oncogene, catalyzes m6A methylation on mRNAs and facilitates cancers invasion, metastasis, and drug resistance." (PMID 34211849, 2021). "Since METTL3 has opposing, context-dependent roles in cancer, interventions to both stimulate and inhibit the activity of METTL3 can be proposed as cancer therapies." (PMID 34315512, 2021). "High levels of METTL3 and the miR-17-92 cluster then enhance the sensitivity of cancer cells to the mTOR inhibitor, everolimus." (PMID 35004679, 2021). "METTL3 methylation in cancer cell lines was distinctly reduced, among which the ES2 cells showed the lowest METTL3 methylation and were thus selected for subsequent analyses." (PMID 34497267, 2021). "These genes have been previously implicated in other cancer types, and RNA m6-A methyltransferases in general have been a topic of recent interest in the new field of cancer epitranscriptomics, with several phase I trials targeting METTL3 due to begin in 2021." (PMID 34556174, 2021).
cancer (continued). "The multiple functions of METTL3 in cancer also indicate the need for exploiting specific METTL3 inhibitors that discriminate m6A-dependent and m6A-independent functions." (PMID 34315512, 2021). "A previous study has shown that METTL3 is a main methyltransferase functioning in methylation processes, which is upregulated in bladder cancer and other malignant tumors in proportion to poor clinical prognosis." (PMID 34497267, 2021). "A study found that miR-33a can inhibit the proliferation and migration of cancer cells by directly binding to the 3′-UTR of METTL3, thus reducing the expression of METTL348." (PMID 34108450, 2021). "When targeting METTL3 in NSCLC, miRNAs can be tumor suppressor genes, as we illustrate above, or oncogenes due to the context-dependent roles of METTL3 in cancer progression." (PMID 34315512, 2021). "Recent studies have found that METTL3 can catalyze m6A modification of mRNA, thereby upregulating the related gene expression and promoting cancer progression." (PMID 34537760, 2021). "The proliferation, migration, and invasion of cancer cells were enhanced with the upregulated expression of METTL3." (PMID 34957092, 2021). "To study the role of PP2Acα and METTL3 in the progression of GC, we performed immunohistochemistry on 10 pairs of GC tissue and normal gastric mucosal tissue adjacent to the cancer." (PMID 34485508, 2021). "The METTL3 knockout can enhance the migration, invasion and adhesion of cancer cells by reducing the level of m6A." (PMID 34489709, 2021). "And in the process of experiment, we found that METTL3 can influence the activity of CD8+ T cells to kill cancer cells." (PMID 34476262, 2021). "In recent years, increasing evidences have shown that METTL3 plays an important role in cancer as an m6A methyltransferase, both as an oncogene and as a tumor suppressor gene." (PMID 34336690, 2021). "Methyltransferase like 3 (METTL3) has been identified to serve as a definitive inducer in cancer progression." (PMID 34666602, 2021). "Altogether, a high expression pattern of METTL3 was identified in ESCA and associated with cancer metastasis." (PMID 34666602, 2021). "Several studies have shown that METTL3 can serve as an oncogene in various cancers such as gastric, bladder, colon, pancreatic and glioblastoma." (PMID 34298617, 2021). "The onset and progression of various cancers are affected by METTL3, either dependent or independent on its m6A RNA methyltransferase activity." (PMID 35117988, 2021). "Most recently, METTL3 inhibitors and other agents targeting RNA epigenetics are emerging as potential cancer therapies with pending clinical trials." (PMID 33879235, 2021). "First, the Pathway Analysis displaying an obviously strong enrichment for pathways in cancer proved the great potential of Mettl3 in regulating BCa progression." (PMID 33681207, 2021). "Far more important, however, these findings provide a mechanistic rational explaining the conserved growth-promoting role of METTL3/14 in cancer models, that remained controversial." (PMID 32761127, 2020). "Among the writers, METTL3 is widely studied and is known to be involved in various types of cancers." (PMID 32709063, 2020). "With the increasing knowledge regarding the regulation, functions, and mechanisms of METTL3 in cancer, it is promising to develop METTL3 targeted agents in the near future." (PMID 32854717, 2020). "These discrepant findings emphasize the complexity of m6A modification and demonstrate that the roles of Mettl3 post-translational modifications in cancer progression and the precise regulatory mechanisms are poorly understood." (PMID 32483411, 2020). "GSEA analyses have demonstrated that cell proliferation and glycolytic pathways in cancer are significantly enriched in response to METTL3 alteration in the CRC cells." (PMID 32245489, 2020).
cancer (continued). "Several lines of evidence have pointed to the involvement of METTL3 in the development and progression of several types of cancer." (PMID 32615646, 2020). "Upregulation of METTL3 contributed to cancer metastasis and predicted poor prognosis in patients with HCC." (PMID 32631107, 2020). "METTL3 regulates oncogene expression by affecting mRNA processing, stability and translation, and it facilitates the progression of different types of cancers, including lung cancer, breast cancer, colorectal carcinoma, bladder cancer 17 and hepatoblastoma." (PMID 33090698, 2020). "METTL3 is responsible for m6A modifications on mRNAs of several crucial oncoproteins related to cell proliferation, migration, and invasion in many cancers." (PMID 32443966, 2020). "Methyltransferase-like 3 (METTL3), a major component of the N6-methyladenosine (m6A) methyltransferase complex, has been suggested to function as an oncogene in several cancers." (PMID 32175271, 2020). "It directly regulates transcription, translation, and RNA maturation of a broad range of oncogene and onco-suppressors, many of which are undiscovered, and the role of METTL3 cancers depends on orchestration of multiple effects." (PMID 33037176, 2020). "Concordantly, METTL3 overexpression is correlated with poor clinical prognosis in all these cancers." (PMID 32296573, 2020). "Since METTL3 was reported to regulate mRNA translation in cancer cells, we decided to explore the role of METTL3 in the regulation of the PI3K/AKT/mTOR signalling pathway." (PMID 33090698, 2020). "METTL3 has been demonstrated to participate in tumorigenesis and the progression of several cancers." (PMID 32631107, 2020). "Further, both in vitro and in vivo data suggested that PDK4 was involved in Mettl3 regulated growth and chemosensitivity of cancer cells." (PMID 32444598, 2020). "Our recent study indicated that METTL3 regulated the epithelial–mesenchymal transition (EMT) of cancer cells via Snail translation." (PMID 31991845, 2020). "Since the function of m6A in eukaryotes involves mRNA degradation 48, we first investigated the effect of METTL3 knockdown in human cancer cells (U2SO, Hela, and A549) and HEK293T cells based on RNA Sequencing analysis." (PMID 32863943, 2020). "Considering the opposite effect of the two “writer” genes in various cancers or even in the same cancer type, more experimental proofs regarding to the exact role of METTL3 and METTL14 in ccRCC are in high demand in future." (PMID 32419773, 2020). "MYC(c-myc) had been discovered as an mRNA target of METTL3-mediated m6A modification by high-throughput RNA-Seq and m6A-Seq in different types of cancer 15,16." (PMID 32284755, 2020). "m6A within the coding sequence of the EMT regulator Snail triggers polysome-mediated translation of Snail mRNA in cancer cells, and deletion of METTL3 impairs cancer cell migration, invasion, and EMT51." (PMID 32296573, 2020). "In most cases, METTL3 was reported as an oncogene to promote the initiation and development of a variety of cancers, including hematopoietic malignancies and solid tumors, through depositing m6A modification on critical transcripts." (PMID 32854717, 2020). "Most studies focus on the function of METTL3 in cancer, and only a few studies have explored why METTL3 expression is abnormal in cancer." (PMID 32429972, 2020). "In view of METTL3’s specific role in different cancers, further studies are still needed to clarify the exact roles of METTL3 in specific type of cancers." (PMID 32615646, 2020). "Methyltransferase-like 3 (Mettl3), an RNA N6-methyladenosine (m6A) methyltransferase, has been shown to act as an oncogene in several human cancers." (PMID 32483411, 2020).
cancer (continued). "To define the molecular basis of the ERRγ in cancer progression, we checked the expression of Mettl3 and ERRγ in xenografts based on HepG2 and HepG2/ADR cells." (PMID 32206097, 2020). "m6A modification also plays an important role in EMT and cancer metastasis by regulating Snail translation in a METTL3- and YTHDF1-dependent manner." (PMID 32111216, 2020). "Several studies have identified that METTL3 can promote cancer cell proliferation and invasion by upregulating downstream key oncogenes via post-transcriptional modification." (PMID 32175271, 2020). "We then evaluated the potential transcription factors (TFs) responsible for the regulation of Mettl3 in cancer cells." (PMID 32444598, 2020). "Our data provided a novel mechanism which was responsible for the upregulation of Mettl3 in cancer cells." (PMID 32444598, 2020). "Although Mettl3 is the most important component of the RNA m6a methyltransferase complex, few studies have directly focused on the role of Mettl3 SUMOylation modification in human diseases, especially in cancers." (PMID 32483411, 2020). "Undoubtedly, METTL3 and its mediation of RNA m6A methylation in cancer are novel prognostic markers and predictive factors in gastrointestinal cancer." (PMID 32429972, 2020). "Hypomethylation of m6A resulting from decreased METTL3 expression was also observed in some cancers." (PMID 32854717, 2020). "Both qRT-PCR and Western blot analysis showed that the expression of TGFβ1 and METTL3 increased in high lung metastasis potential cancer cells compared with that in the parental cells." (PMID 31991845, 2020). "For example, in GC, METTL3 can promote cancer by catalyzing the methylation of either ZMYM1 or HDGF." (PMID 32398132, 2020). "Our recent study showed that deletion of Mettl3 can suppress the epithelial to mesenchymal transition (EMT) of cancer cells by inhibiting translation of Snail12." (PMID 32444598, 2020). "We further tested the potential effects of the METTL3/TGFβ1/Snail axis on the in vivo progression of cancer." (PMID 31991845, 2020). "The results indicated that METTL3 protein levels in most cancer cell lines (except for BGC823 and SUN216) were higher than those in GES-1." (PMID 32175271, 2020). "Conclusively, histone modification and ncRNAs affects the expression and regulation of METTL3, contributing to better understand the physiological functions and regulatory mechanisms of METTL3 in cancers." (PMID 33029866, 2020). "Together, these data suggested that METTL3/ TGFβ1/Snail axis regulates the in vivo progression of cancer." (PMID 31991845, 2020). "One notable example is the N6-adenosine methyltransferase (METTL3) catalyzing N6-adenosine methylation of RNA, which is reported to be essential for the survival of certain cancer types, compared to healthy cells." (PMID 32481522, 2020). "Our study strongly suggests that METTL3/14-directed m6A-modification is a conserved mechanism promoting elevated cell cycle progression in IGF2BP1-expressing cancers." (PMID 32761127, 2020). "Among these enzymes, METTL3 is involved in cancer progression by regulating cancer-related gene expression." (PMID 32650804, 2020). "In other types of cancer, such as endometrial cancer, METTL3 expression was found to be reduced, promoting proliferation by altering AKT signaling." (PMID 33552994, 2020). "METTL3 is overexpressed in pancreatic cancer and promotes cancer cell resistance to gemcitabine, 5-fluorouracil, cisplatin and irradiation." (PMID 32111216, 2020). "Deletion of Mettl3 decreased the expression of PDK4, while over expression of PDK4 can attenuate Mettl3 regulated glycolysis of cancer cells." (PMID 32444598, 2020). "Of the cancer specimens, 69 of 112 cancers (61.6%) had high expression of iASPP and 65 of 112 cancers (58.0%) had high expression of METTL3." (PMID 32201509, 2020). "Research has regarded METTL3 to function as an oncogene that promotes the growth of cancer cells in various cancers such as GC and ovarian carcinoma." (PMID 33048840, 2020).
cancer (continued). "Consistent with the immunohistochemistry, iASPP and METTL3 protein expression in cancer tissues when quantified through western blot analysis in comparison with the β-actin loading control was also significantly higher than that in ANCT." (PMID 32201509, 2020). "Accumulating evidence in recent years reveals that METTL3 plays key roles in a variety of cancer types, either dependent or independent on its m6A RNA methyltransferase activity." (PMID 32854717, 2020). "In LCA, miR-600 decreases the expression of METTL3 and reverses the effect of METTL3 on cancer cell progression." (PMID 32911345, 2020). "m6A was reported to be involved in the EMT of cancer cells and modulated via the methyltransferase METTL3, demethylase ALKBH5, and its reader YTHDF1." (PMID 33364952, 2020). "METTL3 can promote cancer cell growth, survival, and invasion by recruiting eIF3h to the translation initiation complex and directly promotes oncogene translation independently of its MTase activity." (PMID 31921660, 2019). "The increased expression of METTL3 increases m6A abundance, and its growth promoting effect has been validated in a few cancer types." (PMID 31847302, 2019). "It was found that the METTL3 mRNA expression level was higher in lung cancer tissues than in normal tissues from cancer patients." (PMID 31757221, 2019). "Knockdown of METTL3 results in a reduction in m6A and subsequently promotes cancer cell proliferation and invasion by activating PI3K-AKT signaling." (PMID 31921660, 2019). "METTL3 inhibition can induce cancer cell apoptosis by regulating the expression of apoptosis-related genes in an m6A-dependent manner." (PMID 31921660, 2019). "METTL3 was an indicator of poor prognosis and METTL3 silencing inhibited the proliferation, migration, and invasion abilities of cells, colony formation, and motility, demonstrating that METTL3 plays an oncogenic role in these cancers." (PMID 31921660, 2019). "METTL3 acts as an oncogene in cancer cells, enhancing the translation of cancer-inducing genes by interacting with translation initiation factor." (PMID 31110512, 2019). "If the m6A-dependent regulation of SRF expression is conserved, it was investigated by monitoring SRF mRNA and protein abundance upon METTL3/14 depletion in four cancer-derived cells." (PMID 30371874, 2019). "Dysregulation of METTL3 in various cancers can also influence cancer cell EMT, apoptosis, and stem cell self-renewal, which have been identified to be important in cancer progression." (PMID 31921660, 2019). "METTL3 as the main methyltransferase for methylation process has been found to be upregulated in many cancers, including CRC." (PMID 31492150, 2019). "Accumulated evidence has strongly supported that METTL3 is involved in a variety of physiological contexts and in cancers." (PMID 31772500, 2019). "Our statistical and experimental results for the mRNA methyltransferase METTL3 add to the growing evidence of links between mRNA methylation and cancer." (PMID 31363082, 2019). "These authors found that m6A targets parathyroid hormone receptor-1 mRNA and that Mettl3 depletion impairs Pth1r mRNA translation, providing clues about the role of RNA-methylation on estrogen signaling in women’s cancer." (PMID 31426393, 2019). "After METTL3 inhibition, the expression levels of cancer stem cell surface antigens such as CD133, CD44, and epithelial cell adhesion molecule were markedly reduced." (PMID 31921660, 2019). "METTL3 expression is increased in most cancers, while the dysregulation of METTL14 expression is cancer-dependent." (PMID 31847302, 2019). "In the majority of cancer research, METTL3 has been found to be upregulated and to play an oncogenic role accompanied by increased m6A levels compared with those in normal tissues or cell lines." (PMID 31921660, 2019).